PRAMEF12 (PRAME family member 12)
Synonyms: OTTHUMG00000001927
Tractability: PROTAC: ubiquitination databases record sites on it.
Gene: Protein-coding gene on chromosome 1 (12,773,738 to 12,777,906, forward strand). Ensembl gene ENSG00000116726.
Subcellular location (Human Protein Atlas): Nucleoplasm
Gene Ontology:
Molecular function: ubiquitin-like ligase-substrate adaptor activity
Biological process: proteasome-mediated ubiquitin-dependent protein catabolic process; negative regulation of apoptotic process; negative regulation of cell differentiation; negative regulation of DNA-templated transcription; positive regulation of cell population proliferation
Cellular component: Cul2-RING ubiquitin ligase complex; cytoplasm
Genetic constraint (gnomAD): Loss-of-function variants: 24 observed, 25.67 expected, observed/expected ratio (o/e) 0.93, 90% interval 0.68 to 1.32. The upper end of that interval is the gene's LOEUF score, 1.32, which puts it in group 5 of 6, group 1 being the genes least tolerant of losing a copy. Missense variants: 646 observed, 604.85 expected, observed/expected ratio (o/e) 1.07, 90% interval 1 to 1.14. Synonymous variants: 286 observed, 248.71 expected, observed/expected ratio (o/e) 1.15, 90% interval 1.04 to 1.27.
Homologues: Orthologues: chimpanzee PRAMEF12 (96% identical), macaque PRAMEF12 (91% identical), mouse Pramel13 (48% identical), rat Pramef12 (47% identical), mouse Pramel12 (47% identical), rat Pramef8 (47% identical), mouse Pramel31 (45% identical), mouse Gm13040 (44% identical), mouse Gm13043 (44% identical), mouse Gm13057 (44% identical), mouse Pramel16 (44% identical), mouse Pramel28 (44% identical), and 80 more. Paralogues in human: PRAMEF7 (83% identical), PRAMEF8 (82% identical), PRAMEF20 (62% identical), PRAMEF5 (62% identical), PRAMEF6 (62% identical), PRAMEF25 (61% identical), PRAMEF26 (61% identical), PRAMEF15 (61% identical), PRAMEF27 (61% identical), PRAMEF11 (61% identical), PRAMEF9 (61% identical), PRAMEF4 (61% identical), and 12 more.
Diseases named in the same sentence as PRAMEF12 in open-access papers:
PRAMEF12 is named in the same sentence as 3 diseases in open-access papers, as found by Europe PMC text mining. Sharing a sentence is not in itself a finding about the gene and the disease. The quoted sentences say what the papers report.
infertile (1 paper, 2021). "Deletion of Pramef12 leads to smaller testes with a Sertoli cell-only (SCO) phenotype in mature mice that are infertile." (PMID 34074333, 2021).
Sertoli Cell-Only Syndrome (1 paper, 2019). A type of male infertility in which no germ cells are visible in any of the biopsied SEMINIFEROUS TUBULES (type I) or in which germ cells are present in a minority of tubules (type II). "We document that genetic ablation of Pramef12 impairs SSC self-renewal and early differentiation, which prevents sustained cycles of spermatogenesis and results in a Sertoli cell-only syndrome in adult mice." (PMID 31729367, 2019).
PRAMEF12 also shares sentences with these, for which no sentence is quoted: metastatic tumors (1 paper).